SKA3 (spindle and kinetochore associated complex subunit 3)
Description:
Component of the SKA1 complex, a microtubule-binding subcomplex of the outer kinetochore that is essential for proper chromosome segregation. The SKA1 complex is a direct component of the kinetochore-microtubule interface and directly associates with microtubules as oligomeric assemblies. The complex facilitates the processive movement of microspheres along a microtubule in a depolymerization-coupled manner. In the complex, it mediates the microtubule-stimulated oligomerization. Affinity for microtubules is synergistically enhanced in the presence of the ndc-80 complex and may allow the ndc-80 complex to track depolymerizing microtubules.
Synonyms: C13orf3; RAMA1; MGC4832
Tractability: PROTAC: ubiquitination databases record sites on it.
Gene: Protein-coding gene on chromosome 13 (21,153,594 to 21,176,602, reverse strand). Ensembl gene ENSG00000165480.
Subcellular location: Cytoplasm, cytoskeleton, spindle; Chromosome, centromere, kinetochore
Subcellular location (Human Protein Atlas): Centrosome; Mitotic spindle; Cytosol
Gene Ontology:
Molecular function: microtubule binding; protein binding
Biological process: attachment of mitotic spindle microtubules to kinetochore; metaphase chromosome alignment; mitotic metaphase chromosome alignment; mitotic sister chromatid segregation; negative regulation of mitotic spindle assembly checkpoint signaling; regulation of microtubule polymerization or depolymerization; chromosome segregation; establishment of meiotic spindle orientation; mitotic cell cycle; spindle assembly involved in female meiosis
Cellular component: centrosome; kinetochore; mitotic spindle; outer kinetochore; SKA complex; spindle microtubule; meiotic spindle; spindle
Genetic constraint (gnomAD): Loss-of-function variants: 24 observed, 27.98 expected, observed/expected ratio (o/e) 0.86, 90% interval 0.62 to 1.21. The upper end of that interval is the gene's LOEUF score, 1.21, which puts it in group 5 of 6, group 1 being the genes least tolerant of losing a copy. Missense variants: 471 observed, 431.27 expected, observed/expected ratio (o/e) 1.09, 90% interval 1.01 to 1.18. Synonymous variants: 177 observed, 156.54 expected, observed/expected ratio (o/e) 1.13, 90% interval 1 to 1.28.
Homologues: Orthologues: chimpanzee SKA3 (99% identical), macaque SKA3 (94% identical), dog SKA3 (78% identical), rabbit SKA3 (73% identical), guinea pig SKA3 (66% identical), pig SKA3 (64% identical), rat Ska3 (63% identical), mouse Ska3 (63% identical), tropical clawed frog ska3 (36% identical), zebrafish ska3 (24% identical).
Diseases named in the same sentence as SKA3 in open-access papers:
SKA3 is named in the same sentence as 48 diseases in open-access papers, as found by Europe PMC text mining. Sharing a sentence is not in itself a finding about the gene and the disease. The quoted sentences say what the papers report.
cervical cancer (16 papers, 2018 to 2025). A primary or metastatic malignant neoplasm involving the cervix. "The member SKA3 was associated with proliferation and migration of cancer cells and tumor growth in patients with cervical cancer." (PMID 35095717, 2021). "Spindle and kinetochore associated complex subunit 3 (SKA3) plays a key role in cervical cancer development, but its contribution to LUAD is unknown." (PMID 32068236, 2020). "SKA3 promotes the malignant progression of cervical cancer cells through the activation of the PI3K/AKT signaling pathway." (PMID 41298345, 2025). "SKA3 is highly expressed in malignant tumors such as colon cancer, liver cancer, cervical cancer, and prostate cancer and plays an important role in cancer occurrence and development." (PMID 35295342, 2022). "SKA3 expression is also increased in cervical cancer tissues, and cervical cancer patients with high SKA3 expression have a poor prognosis." (PMID 34045512, 2021). "SKA3 overexpression promotes cervical cancer cell proliferation and migration and accelerates tumor growth." (PMID 34045512, 2021). "In cervical cancer, SKA3 activates PI3K-Akt signaling, regulates cell cycle progression, and exacerbates tumors." (PMID 34572901, 2021). "SKA3 overexpression promotes the growth and migration of cervical cancer cells by activating the PI3K-AKT signaling pathway and promoting cell cycle progression." (PMID 32528520, 2020). "Similar to the present study, recent findings indicated that SKA3 promotes cell proliferation and migration in cervical cancer tissue through its ability to activate PI3K/Akt signaling." (PMID 32068236, 2020). "Besides, SKA3 promotes lung adenocarcinoma and cervical cancer metastasis by regulating the cell cycle and the PI3K/Akt pathway." (PMID 34993016, 2021). "Previous studies reported that SKA3 promotes the proliferation and migration of lung adenocarcinoma and cervical cancer cells through the PI3K-Akt axis, suggesting that the PI3K-Akt pathway may be critical for SKA3 to promote tumor formation, invasion, and metastasis." (PMID 34993016, 2021). "Thus, we propose that SKA3 overexpression promotes cervical cancer cell proliferation and migration by regulating the cell cycle and the PI3K/Akt pathway, which might suggest a new strategy for finding novel targetable pathways in CC." (PMID 30459531, 2018). "The analyses of GSEA and RNA-Seq showed the significant participation of SKA3 in the regulation of the PI3K/Akt signaling pathway and the progression of cell cycle in cervical cancer." (PMID 36439516, 2022). "It has been shown that Ska3 upregulation activates PI3K/Akt signaling pathway, which promotes cell proliferation in cervical cancer." (PMID 35883647, 2022). "Previous studies showed that SKA3 plays important roles in the pathogenesis and exacerbation of hepatocellular carcinoma (HCC), cervical cancer, and other malignancies." (PMID 34572901, 2021). "pointed out that upregulation of SKA3 elevated the expression of CDK4, p-Akt, Cdk2 cyclinE2, p-Rb, E2F1, and cyclinD1 in HeLa cells, thus promoting cervical cancer proliferation and migration." (PMID 34845974, 2021). "Previous studies reported that SKA3 could promote PI3K/AKT pathway to accelerate cell proliferation and migration in cervical cancer." (PMID 35546682, 2022). "Moreover, it has been reported that SKA3 can facilitate PI3K/AKT signaling pathway to promote cell cycle and progression in cervical cancer." (PMID 32180800, 2020).
lung adenocarcinoma (10 papers, 2019 to 2026). A carcinoma that arises from the lung and is characterized by the presence of malignant glandular epithelial cells. "Upregulation of SKA3 and associated cancer progression have also been reported in other tumors, including lung adenocarcinoma, prostate cancer, breast cancer, glioma, kidney renal papillary cell carcinoma, skin cutaneous melanoma and bladder cancer." (PMID 38791174, 2024). "SKA3 is implicated in the development and progress of lung adenocarcinoma, prostate cancer, cervical cancer, and breast cancer." (PMID 33106477, 2020). "In the present research, we analyzed the expression level of SKA3 in lung adenocarcinoma tissues, and the association between SKA3 expression and the clinic-pathological features of lung adenocarcinoma patients." (PMID 33817174, 2019). "The mRNA expression level of SKA3 in lung adenocarcinoma and its association with clinic-pathological factors were analyzed using data obtained from the TCGA database." (PMID 33817174, 2019). "Kaplan-Meier analysis showed that high SKA3 expression is markedly associated with poor prognosis in lung adenocarcinoma patients." (PMID 33817174, 2019). "In conclusion, this study clearly demonstrated that the up-regulation of SKA3 expression is positively associated with lower disease-free survival in lung adenocarcinoma patients." (PMID 33817174, 2019). "SKA3 expression was enhanced and associated with poor prognosis in lung adenocarcinoma patients, and it might play a facilitating role in cell growth and motility by regulating the MAPK signaling pathway." (PMID 33817174, 2019). "Kaplan-Meier analysis showed that higher SKA3 expression is associated with lower overall survival rates, indicating that SKA3 might be a prognosis predictor in lung adenocarcinoma patients." (PMID 33817174, 2019). "In lung adenocarcinoma, SKA3 was identified as an oncogene promoting cell growth and migration by PLK1-mediated SKA3 phosphorylation and stimulating metastasis through the activation of PI3K-AKT signaling." (PMID 38791174, 2024). "For example, SKA3 promotes lung adenocarcinoma metastasis by binding to EFGR and activating PI3K-AKT signaling." (PMID 36874921, 2023). "In lung adenocarcinoma, SKA3 promoted metastasis by binding to EGFR and activating the PI3K/AKT signaling pathway." (PMID 36439516, 2022). "SKA3 upregulation in lung adenocarcinoma cells correlates with increased metastases and tumor growth." (PMID 33224872, 2020). "The correlation between SKA3 expression and the clinic-pathological characteristics of 483 lung adenocarcinoma patients." (PMID 33817174, 2019). "Collectively, these data suggested that SKA3 contributes to promoting lung adenocarcinoma cell growth and motility." (PMID 33817174, 2019). "In the present study, we also observed the up-regulation of SKA3 in lung adenocarcinoma compared with that in normal lung tissues based on the mRNA expression data obtained from the public database." (PMID 33817174, 2019). "The expression of SKA3 is notably higher in the lung adenocarcinoma samples than in the normal lung samples (p<0.0001)." (PMID 33817174, 2019). "The expression of SKA3 in lung adenocarcinoma tissues (N=535) and normal tissues (N=59) was analyzed based on the data get from TCGA database." (PMID 33817174, 2019). "The objective of this research is to investigate the expression and function of SKA3 in lung adenocarcinoma." (PMID 33817174, 2019). "Here, we initially studied the mRNA expression level of SKA3 in lung adenocarcinoma tissues based on the public database and determined that it is overexpressed in lung adenocarcinoma tissues compared to the normal lung tissues." (PMID 33817174, 2019). "We found that SKA3 is up-regulated in lung adenocarcinoma compared to the normal lung tissues." (PMID 33817174, 2019).
lung adenocarcinoma (continued). "A total of 483 lung adenocarcinoma cases with complete clinical data were obtained from TCGA database and divided into a high expression group (N=242) and low expression group (N=241) according to the median of SKA3 expression." (PMID 33817174, 2019). "Also, in other tumors, it had been demonstrated that the high expression of SKA3 was closely related to the pathological and clinical features and poor prognosis of liver cancer, lung adenocarcinoma, rectal cancer, and other tumors, which was consistent with our results." (PMID 34993016, 2021). "However, the expression and role of SKA3 in lung adenocarcinoma needs to be further investigated." (PMID 33817174, 2019). "Moreover, we also explored the role of SKA3 in lung adenocarcinoma cell growth and migration." (PMID 33817174, 2019). "For instance, SKA3 binds EGFR and consequently activates PI3K–AKT, thus promoting lung adenocarcinoma metastasis." (PMID 33106477, 2020).
breast carcinoma (7 papers, 2013 to 2025). "In the female patients with early breast cancer, the close association of the elevated SKA3 expression with a poor prognosis was observed." (PMID 36439516, 2022). "To further search for the SKA3-associated PPI network in breast cancer, we performed a correlation analysis using the STRING database." (PMID 34993016, 2021). "Kaplan–Meier curves implicated that high SKA3 expression was related to a poor prognosis in female early breast cancer patients." (PMID 34993016, 2021). "Cox regression models showed that high SKA3 expression could be used as an independent risk factor for female early breast cancer." (PMID 34993016, 2021). "Previous studies reported that SKA3 frequently mutates in breast cancer and might be a potential oncogene of breast cancer." (PMID 34993016, 2021). "It was speculated that overexpression of SKA3 might cause abnormalities of the mitotic spindle or close the mitotic checkpoint, promoting cell proliferation, leading to the generation of breast cancer." (PMID 34993016, 2021). "Multiple studies have shown that SKA3 is closely related to the malignant progression and poor prognosis of various cancers, including melanoma, bladder cancer, and breast cancer." (PMID 41298345, 2025). "The RT-qPCR showed that the SKA3 mRNA in 66 pairs of breast cancer tissues was higher than that in adjacent tissues (P < 0.01)." (PMID 34993016, 2021). "It seemed that SKA3 expression affected immune cell content in the breast cancer tumor microenvironment, exerting both antitumor and protumor functions." (PMID 34993016, 2021). "Both log-rank test and Cox proportional hazards model showed that expression of SKA3 was significantly correlated with the prognosis of breast cancer." (PMID 34993016, 2021). "SKA1 and SKA3 genes are immunotherapy-related biomarkers in breast cancer and breast cancer stem cells." (PMID 34993016, 2021). "In all molecular subtypes, SKA3 mRNA expression is the highest in TNBC breast cancer and the lowest in luminalA breast cancer (P < 0.0001)." (PMID 34993016, 2021). "Using the TCGA database to analyze the expression of SKA3, it was also found that SKA3 expression in breast cancer tissues was higher than that in normal (adjacent) tissues." (PMID 34993016, 2021). "Besides, the SKA3 expression level was associate with infiltrating levels of activated CD4 T cells and eosinophils in breast cancer." (PMID 34993016, 2021). "SKA3 mRNA was expressed at high levels in breast cancer tissues compared with normal tissues." (PMID 34993016, 2021). "On top of that, SKA3 expression may be an independent predictor of a poor disease survival prognosis in breast cancer patients." (PMID 34993016, 2021). "Further studies are needed to explore the mechanism of SKA3 in breast cancer." (PMID 34993016, 2021). "It was surmised that the expression level of SKA3 might serve as a candidate biomarker to evaluate the prognosis of breast cancer patients." (PMID 34993016, 2021). "It was speculated that SKA3 might be an upstream gene of MYC, and the high expression of SKA3 might activate MYC oncogene and promote tumor progression, which was associated with poor survival outcomes of breast cancer." (PMID 34993016, 2021). "High SKA3 expression correlates with poor prognosis and immune infiltrates in breast cancer and may become a biomarker for the prognosis of breast cancer." (PMID 34993016, 2021). "Besides, the high SKA3 expression group was negatively correlated with estrogen response early which was closely related to the progression of breast cancer." (PMID 34993016, 2021). "Besides, ELISA showed that SKA3 protein expression in 38 pairs of BC tissues was over-expressed in breast cancer tissues than that in adjacent tissues, (P < 0.001), which is corresponding to RT-qPCR results." (PMID 34993016, 2021). "Our study aimed to investigate the importance of SKA3 in breast cancer." (PMID 34993016, 2021).
breast carcinoma (continued). "It was suggested that breast cancer with overexpression of SKA3 might be more malignant and aggressive." (PMID 34993016, 2021). "The study aimed to explore the prognostic significance of SKA3 in breast cancer." (PMID 34993016, 2021). "In summary, SKA3 was overexpressed in ER-negative, PR-negative, triple-negative breast cancer both in the whole TCGA cohort, Asian-specific group in TCGA and our Asian-specific validating cohort in female breast cancer." (PMID 34993016, 2021). "High SKA3 expression correlates with poor prognosis and immune infiltrates in breast cancer." (PMID 34993016, 2021). "But the relationship between SKA3 and early breast cancer remains unclear." (PMID 34993016, 2021). "SKA3 may become a biomarker for the prognosis of breast cancer." (PMID 34993016, 2021). "RNA interference-mediated suppression of five candidate genes (DDX10, SKA3, EPHA5, CLTC and TNIK) led to inhibition of breast cancer cell growth." (PMID 23496902, 2013). "In combination with the previous study and our GSEA results, it was speculated that SKA3 might activate the PI3K-Akt-mTORC1 pathway and promote the occurrence and development of breast cancer." (PMID 34993016, 2021). "We speculated that high-expressed SKA3 might impact the eosinophil and activated CD4 T cells, triggering a disadvantageous immune response, leading to a poor prognosis in breast cancer." (PMID 34993016, 2021). "Using whole genome mate pair sequencing and RNA interference assays, we have discovered a number of novel gene rearrangements in breast cancer genomes and identified DDX10, SKA3, EPHA5, CLTC and TNIK as potential cancer genes with impact on the growth and proliferation of breast cancer cells." (PMID 23496902, 2013). "At present, there has been no report on SKA3 in predicting the prognosis of breast cancer." (PMID 34993016, 2021). "The potential biological functions of SKA3 in breast cancer had not yet been fully clarified." (PMID 34993016, 2021). "However, SKA3 expression and its role in early breast cancer have not yet been reported." (PMID 34993016, 2021).
hepatocellular carcinoma (6 papers, 2019 to 2024). A malignant tumor that arises from hepatocytes. "The molecular mechanism of SKA3 promoting the proliferation of hepatoma cells will be further studied in the future, which will provide a solid foundation for the prevention and treatment of liver cancer." (PMID 31804459, 2019). "This suggests that the expression of SKA3 is elevated in human hepatocellular carcinoma and positively correlated with the malignancy of the tumor." (PMID 31804459, 2019). "Overall, these findings uncover the role of SKA3 in regulating the apoptosis and proliferation of hepatocellular carcinoma cells." (PMID 31804459, 2019). "Bioinformatics analysis found that hepatocellular carcinoma patients with high levels of expression of SKA3 have a poor prognosis." (PMID 31804459, 2019). "The aim of this study was to explore the regulatory mechanism of SKA3 on the invasion and proliferation of hepatoma cells." (PMID 31804459, 2019). "Similarly, the expression of SKA3 was upregulated in hepatocellular carcinoma tissues compared to adjacent tissues, and the knockdown of SKA3 can significantly accelerate cell apoptosis and inhibit tumor proliferation and invasion in vivo and in vitro." (PMID 34845974, 2021). "Hepatocellular carcinoma patients with high levels of SKA3 expression have a poor prognosis." (PMID 33670062, 2021). "In order to study the role of SKA3 in hepatocellular carcinoma (HCC), three kinds of siRNA targeting SKA3 (siRNA-1, siRNA-2, and siRNA-3) were transfected into LM3 and Huh7 cell lines, and siRNA was transfected as control." (PMID 31804459, 2019). "Genes, such as CHAF1B, INHBA, TGFB2, SKA3, and HELLS, are responsible for the invasion of various cancer cells, such as hepatocellular carcinoma, gastric cancer cells, renal cell carcinoma, prostate cancer, head and neck cancer, but these genes may be involved in the invasion of BRCA cells." (PMID 31311202, 2019). "However, the relationship between SKA3 and hepatocellular carcinoma (HCC) has not yet been fully elucidated." (PMID 31804459, 2019).